INS (insulin)
Diseases named in the same sentence as INS in open-access papers (continued):
Sharing a sentence is not in itself a finding about the gene and the disease.
Obesity (continued). "Systemic inhibition of the TOR pathway prevents high-fat diet (HFD)-induced obesity and cardiac dysfunction, indicating that deregulation of the insulin-TOR axis is responsible for deleterious HFD-induced effects." (PMID 27604692, 2016). "HbA1c (hemoglobin A1c) level ≥8.5 %, obesity and insulin treatment in dose-dependent and time-varying manner demonstrated significant association with increased risk of malignancy, while metformin use was associated with a lower risk of cancer." (PMID 27724912, 2016). "Concentrations of maternal serum IGF-I and leptin are decreased in intrauterine growth restriction (IUGR) while pregnancies associated with obesity and diabetes have higher maternal serum IGF-I, insulin, and leptin." (PMID 26858656, 2016). "These protective effects of omentin in both obesity and cardiovascular disease seem to be based on disease-specific effects, for example, an insulin sensitizing effect in obesity and modulation of NO synthase function in the coronary endothelium." (PMID 27867249, 2016). "Given the observed clustering of obesity, hypertension, inflammation, intermittent hypoxia, hyperglycemia, and insulin and leptin resistance, studies in humans in this area are extremely difficult and require innovative experimental approaches." (PMID 26781642, 2016). "The suppression of Rap1 protect against obesity and metabolic disorders through the regulation of food intake and maintaining leptin and insulin signaling." (PMID 27812350, 2016). "Our results are in line with studies showing that reducing circulating insulin with diazoxide, partial ablation of the Ins1 gene or the inhibition of insulin signalling by genetic or pharmacological approaches protects from obesity and the metabolic syndrome." (PMID 27677764, 2016). "In support of this suggestion, obestatin has been shown to reduce obesity-induced increases in inflammatory cytokines, to decrease insulin sensitivity and to decrease triglyceride levels." (PMID 27471436, 2016). "Type 2 diabetes is associated with cognitive impairment but the relationship of its precursors, obesity and elevated insulin, to cognition has been less studied." (PMID 27642517, 2016). "PPARs are key nuclear receptor isoforms in the regulation of lipid and glucose metabolism, which play an important role in the regulation of obesity-related insulin sensitivity and inflammation." (PMID 27877172, 2016). "In summary, we have found that mice deficient in FXIII-A show characteristics of metabolically healthy obesity with improved insulin sensitivity." (PMID 27759118, 2016). "Obesity then alters insulin sensitivity by triggering different key steps along the insulin-signaling pathway." (PMID 27136447, 2016). "Accordingly, both PCOS classifications were affected by impaired insulin action, closely related to obesity as well as androgen excess." (PMID 27505055, 2016). "Risk factors that contribute to the development of hypertension include differing concentrations of sodium and potassium in the body, obesity, resistance to insulin, high alcohol intake, low calcium intake, stress and ageing." (PMID 26999166, 2016). "Obesity can affect brain structure, leptin/insulin dysregulation, oxidative stress, cerebrovascular function, blood-brain barrier, and inflammation, which are involved in the deterioration of cognitive and motor functions." (PMID 26881095, 2016). "Till now, knowledge about the role of DA in peripheral tissues during obesity has been limited to its influence on pancreatic β cells regulating insulin release and to the modulation of insulin effects on adipocytes." (PMID 26808524, 2016). "It has been reported that omentin-1 is involved with insulin activity, induces Akt phosphorylation, and is inversely correlated with obesity." (PMID 27721574, 2016).
Obesity (continued). "Despite these shortcomings our study is one the very few to report on the relationship of leptin and adiponectin with lipid profile, anthropomorphic indexes of obesity and insulin sensitivity among subjects of African ancestry." (PMID 27189377, 2016). "Diet-induced obese dams also had higher blood glucose and plasma insulin concentrations compared to lean dams during an oral glucose tolerance test (OGTT) that was performed following obesity induction." (PMID 26868870, 2016). "SCFA have been shown to increase Treg frequency and alleviate AAI, as well as improve insulin metabolism and decrease fat accumulation in obesity." (PMID 27483441, 2016). "Deletion of SF-1 in the VMH resulted in dysregulated insulin and leptin homeostasis and late onset obesity due to increased food intake under normal chow and high fat diet conditions." (PMID 27598259, 2016). "To further characterise the effects of lower insulin levels and attenuated obesity in HFD-fed Ins1−/−:Ins2+/− mice, we measured lipids and metabolic factors in plasma from fasted 40-week-old mice." (PMID 26155745, 2015). "Obesity is increasing in prevalence, and is characterised by a pro-inflammatory and insulin resistant state." (PMID 26110385, 2015). "Other feature of hypertrophic adipocytes is that they show poor sensibility to insulin, due to the reported affectation of membrane receptors as consequence of obesity." (PMID 26869866, 2015). "Both the blood glucose levels and insulin levels belonged to the same cluster, which also contained obesity-related variables, including BMI, waist circumference, and VFA." (PMID 26156880, 2015). "The current study adds to the available literature examining the role of ECs in obesity and glucose and insulin homeostasis." (PMID 25874237, 2015). "In apparent conflict with a protective role for CD80/CD86 in obesity-associated IR, one group of investigators reported that CTLA-4-IgG1 administration improved insulin sensitivity in DIO mice." (PMID 26146464, 2015). "Drosophila mutants in the obesity category included orthologs to human genes impacting metabolism (including lnk involved in insulin signaling), sensory inputs, and immunity." (PMID 26202798, 2015). "Our findings suggest that lipid, obesity-inflammation, and insulin sensitivity domains predominantly exist among obese children." (PMID 26011530, 2015). "Overexpression of UCP in skeletal muscle of mice enhances responsiveness to insulin, improves glucose transport in skeletal muscle, and increases resistance to obesity." (PMID 26064426, 2015). "Obesity is characterised also by a low grade of chronic inflammation, and in addition mechanisms inducing insulin resistance, mediated by pro-inflammatory cytokines have been described." (PMID 25706863, 2015). "The aim of this study was to investigate the effects of TRPM5 gene ablation on body weight, insulin sensitivity and other metabolic parameters in long-term high caloric diet induced obesity." (PMID 26397098, 2015). "Subjects with family history of CAD, hypertension, obesity, smoking, insulin, and hyperlipidemia percentages were significantly higher in CC genotype carriers (all p < 0.05), likewise for BMI, LDL-C, and TG values." (PMID 26417150, 2015). "Adipocyte size is closely correlated with adipocyte function, insulin sensitivity, and metabolism in obesity." (PMID 25768116, 2015). "Zucker rats develop severe obesity and are hyperleptinemic, hyperphagic, inactive, obese, and insulin resistant (hyperinsulinemia, mild hyperglycemia, and hyperlipidemia)." (PMID 26064924, 2015). "Insulin-induced enhancement of myocardial blood flow is blunted in obesity but also serum leptin, a hormone produced by adipose tissue, is inversely related to the adenosine-stimulated myocardial flow suggesting a vasoactive role." (PMID 26124827, 2015). "These paracrine effects enhance insulin-induced vasodilation in lean mice, are mediated by adipokines and are abolished in obesity." (PMID 26003324, 2015).
Obesity (continued). "Adiponectin, an adipocyte-derived insulin-sensitizing and anti-inflammatory hormone, is suppressed in obesity through mechanisms involving chronic inflammation and oxidative stress." (PMID 26030149, 2015). "In diet-induced obesity, Apoe−/− display steatohepatitis but reduced accumulation of triacylglycerides and enhanced insulin sensitivity in white adipose tissue (WAT)." (PMID 26695075, 2015). "Similar to Plin knockout mice, genetic ablation of Cidea or Cidec results in a lean phenotype, enhanced insulin sensitivity, and resistance to dietary induced obesity." (PMID 26176546, 2015). "Intriguingly, TF/FVIIa signalling promotes high-fat diet-induced obesity, adipose tissue inflammation and insulin resistance in mice." (PMID 26271343, 2015). "Endoplasmic reticulum (ER) stress and inflammation induced by obesity lead to adipocyte dysfunction, with the impairment of the insulin pathway." (PMID 25647410, 2015). "To date, few studies in elderly humans have investigated the links between properties of skeletal muscle mitochondria and obesity, body composition, body fat distribution, and insulin sensitivity." (PMID 26448868, 2015). "Other studies have shown that genetic variations in several known imprinted genes, such as IGF2, INS and GNAS, have been associated with CMR traits, including adult obesity (BMI) and T2D." (PMID 26451733, 2015). "Summarising, we have found that PVAT adipocyte size partly explains the relationship between obesity and blunted insulin-induced microvascular recruitment through direct regulation of insulin’s microvascular effects." (PMID 26003324, 2015). "We used independent samples t-test to compare the group differences of plasma glucose, insulin and the rating of hunger (in the subjects with obesity and lean male subjects)." (PMID 26099208, 2015). "Db/db mice exhibit characteristic features of Type 2 diabetic metabolic disorders, including obesity, hyperglycemia, and insulin resistant." (PMID 25909991, 2015). "Short-term diet reversal in animal models can improve insulin sensitivity and glucose homeostasis, reduce some markers of peripheral inflammation, and decrease levels of soluble, oligomeric Aβ, and may thereby improve some of the cognitive impairments associated with obesity, IR, and HFDs." (PMID 26340637, 2015). "Here, as well as in our previous study, we showed that high liver fat is associated with several preclinical metabolic aberrations in obesity, including increased glucose, insulin, lipid, and CRP levels." (PMID 25866590, 2015). "In the present study, we found that prevalence of adult MetS was significantly higher in the insulin-resistant obesity group than in the insulin-sensitive obesity group." (PMID 26640243, 2015). "Increased phosphorylation of S6K1 and 4EBP1 in the pancreatic β-cells of mice improved insulin secretion and resistance to streptozotocin toxicity and obesity." (PMID 26083118, 2015). "Across all studies, l-ascorbic acid was associated with smoking status, alcohol intake, physical activity, and socioeconomic position alongside obesity, insulin, C-reactive protein, IL-6, and urate (where available)." (PMID 25527764, 2015). "In summary, we have shown that treating mice with MnTBAP ameliorates diet-induced obesity and improves in vivo insulin action." (PMID 26397111, 2015). "Androgen signaling in adipose tissue of murine models protects against obesity and regulates insulin action and glucose homeostasis, and AR knockout mice are more susceptible to high-fat diet–induced visceral obesity." (PMID 26445145, 2015). "Research has shown that methods which limit or reduce peripheral hyperinsulinemia in insulin resistant individuals have the potential to treat or prevent obesity and related disease." (PMID 26225266, 2015).
Obesity (continued). "A factor analysis identified three domains that explained 74.08% of the total variance among the obese children (factor 1: lipid, 46.05%; factor 2: obesity-inflammation, 15.38%; factor 3: insulin sensitivity domains, 12.65%)." (PMID 26011530, 2015). "Circulating levels are thought to increase in obesity and insulin resistant states, and elevated visfatin levels have been shown in T2DM." (PMID 26110385, 2015). "Our results identified three domains with regard to the sample of obese children: lipid, obesity-inflammation, and insulin sensitivity." (PMID 26011530, 2015). "There is also a need for more research regarding cancer prevention interventions that counteract the effects of obesity-related elevations in insulin/IGF signaling." (PMID 26029167, 2015). "We previously demonstrated that inducible nitric oxide synthase (iNOS) in the liver plays an important role in hepatic insulin resistance in the setting of obesity." (PMID 26172834, 2015). "An ideal NASH animal model should closely resemble the features of human NASH and include features such as obesity, insulin resistance, and histological changes including liver inflammation and fibrosis." (PMID 26090514, 2015). "In summary, in the presence of genetic or obesity-induced concurrent insulin and leptin resistance, Kiss1 neurons are able to maintain reproductive function." (PMID 25946091, 2015). "When the multivariate generalized linear model was used, the PROX1 CC genotype was associated with VAT/SAT ratio [OR 1.5 (1.01–2.3), p = 0.041] adjusted for age, gender, BMI, fasting insulin, diet and/or treatment of obesity." (PMID 25601634, 2015). "Among possible candidates is adiponectin, an adipose tissue derived adipokine with insulin sensitizing properties, found reduced in obesity." (PMID 26269425, 2015). "Etv5 knockout mice exhibit lean bodies, resistance to diet-induced obesity and severe glucose intolerance due to impaired insulin exocytosis and hypoinsulinaemia." (PMID 25825681, 2015). "In the present study, we examined the relationships between CORT, insulin, obesity, and mental illness." (PMID 25754523, 2015). "Multivariate analysisdemonstrated that most of the differences in HDL-C levels between Germans and Turkswere explained by ethnicity, independently of obesity markers, insulin, and SHBGlevels." (PMID 25647406, 2015). "Meanwhile, PPARβ/δ is ubiquitously expressed, abundantly present in skeletal muscle and, when stimulated, can reduce obesity and improve insulin sensitivity." (PMID 26694920, 2015). "In contrast, obesity-resistant pups cross-fostered to genetically obese dams showed a diet-induced increase in adiposity, reduced insulin sensitivity and associated changes in hypothalamic neuropeptide, insulin, and leptin receptors, which might have contributed to their metabolic defects." (PMID 25926796, 2015). "Studies conducted in rodents have found only a few days of high-fat feeding are sufficient to induce liver steatosis and hepatic insulin resistance, before any change in systemic metabolic function and inflammation occurs before the development of obesity." (PMID 26102213, 2015). "G0S2 knockout mice are lean, resistant to obesity by high fat feeding, glucose tolerant, insulin sensitive, and are more thermogenic." (PMID 26318046, 2015). "These low prevalence rates show the need to promote physical activity because of its association with favorable effects on most CRFs, namely, abdominal obesity, dyslipidemia, global obesity, insulin sensitivity, and blood pressure." (PMID 26380280, 2015). "The lipid domain made a greater contribution than the obesity-inflammation and insulin sensitivity domains among obese participants." (PMID 26011530, 2015). "T-cells are known to play a role in inflammatory myopathies, muscular dystrophies, and obesity-related muscle fat accumulation and insulin resistance." (PMID 26793125, 2015).
Obesity (continued). "Specific correlations exist between different ECs and markers of obesity and insulin and glucose homeostasis." (PMID 25874237, 2015). "Recombinant adiponectin administration is sufficient to improve glucose, lipid, and insulin plasma levels as well as insulin receptor expression and liver steatosis in high fat diet-induced obesity mice treated with streptozotocin." (PMID 25918733, 2015). "Univariate correlations between ADCY5 mRNA expression in visceral (VAT) and subcutaneous (SC) adipose tissue and parameters of obesity, insulin sensitivity, and inflammation." (PMID 25793868, 2015). "Recently adipose tissue derived hormone leptin together with other adipocytokines affect insulin sensitivity and is accepted to play a role in pathogenesis of obesity-related disorders." (PMID 26569494, 2015). "This female-specific FTO effect has also been reported previously related to obesity, insulin sensitivity and glucose levels in children." (PMID 26445370, 2015). "The important role of IFN-γ in regulating IR in obesity was suggested because insulin sensitivity in obese IFN-γ-knockout animals improved in comparison with obese wild-type control animals." (PMID 26039731, 2015). "Inversely, obesity-induced elevations in insulin and leptin are features of the metabolic syndrome and individually exert suppressive effects on steroidogenesis in the testes." (PMID 26366723, 2015). "The results showed that berberine actually increases insulin sensitivity and is capable of inhibiting alpha glucosidase, adipogenesis, and thus acts as an anti-obesity and hypoglycemic agent." (PMID 26693406, 2015). "The level of aromatase activity is a function not only of the total adipose tissue mass, but also, and of particular significance in the present context, the extent of enzyme induction per unit cell by obesity-related mediators, including insulin." (PMID 26516917, 2015). "The HFD-fed Ins1−/−:Ins2+/− female mice maintained protection against obesity into adulthood, despite the fact that their suppression of fasting insulin had reverted by 1 year." (PMID 26155745, 2015). "Next, I will provide an overview of the central mechanisms for regulating body weight, including a discussion of central leptin/insulin resistance during aging and obesity." (PMID 26236282, 2015). "Our study was merely a superficial observation of the contact of insulin and P-glycoprotein in gastric cancer with obesity." (PMID 26084465, 2015). "Results show that some if not most of our middle-aged rhesus monkeys were confirmed to have obesity, β-cell impairment, insulin level decline and persistent hyperglycemia verifying the development of spontaneous T2DM." (PMID 26113016, 2015). "Disadvantages of subcutaneous administration of insulin are hypoglycemia, peripheral hyperinsulinemia, lipoatrophy, lipohyperatrophy, obesity due to intensive therapy, insulin neuropathy and insulin presbyopia." (PMID 26498972, 2015). "In this way, the development of obesity can be seen as a consequence of inappropriate/insufficient sympathetic control, energy dissipation, gaining weight and then insulin resistance." (PMID 26069728, 2015). "Perpetual caloric excess in individuals with obesity disrupts the intricate balance between energy storage and mobilization, leading to desensitization of tissues to the actions of insulin and the development of IR." (PMID 26720346, 2015). "In support of this notion, augmenting the antioxidant defense system in mice improves insulin action in the setting of obesity." (PMID 26397111, 2015). "An HLA haplotype (HLA-DRB1*02) protective for T2DM and associated with increased insulin secretion was identified among Pima Indians, a group with high rates of T2DM and obesity but low prevalence of GAD2 and other known islet cell antibodies." (PMID 26606528, 2015).